CCDC78 (coiled-coil domain containing 78)
Description:
Component of the deuterosome, a structure that promotes de novo centriole amplification in multiciliated cells that can generate more than 100 centrioles. Deuterosome-mediated centriole amplification occurs in terminally differentiated multiciliated cells (G1/0) and not in S phase. Essential for centriole amplification and is required for CEP152 localization to the deuterosome.
Synonyms: C16orf25; JFP10; FLJ34512; CNM4; hsCCDC78
Tractability: Antibody: its Gene Ontology location is reachable by antibodies, with high confidence; UniProt places it where antibodies can reach, with medium confidence.
Gene: Protein-coding gene on chromosome 16 (722,581 to 726,954, reverse strand). Ensembl gene ENSG00000162004.
Subcellular location: Cytoplasm, cytoskeleton, microtubule organizing center, centrosome, centriole; Cytoplasm, perinuclear region; Cell membrane, sarcolemma; Sarcoplasmic reticulum
Gene Ontology:
Biological process: de novo centriole assembly involved in multi-ciliated epithelial cell differentiation; skeletal muscle contraction
Cellular component: centriole; deuterosome; perinuclear region of cytoplasm; sarcolemma; sarcoplasmic reticulum; cytoplasm
Genetic constraint (gnomAD): Loss-of-function variants: 78 observed, 58.31 expected, observed/expected ratio (o/e) 1.34, 90% interval 1.11 to 1.62. The upper end of that interval is the gene's LOEUF score, 1.62, which puts it in group 6 of 6, group 1 being the genes least tolerant of losing a copy. Missense variants: 737 observed, 601.48 expected, observed/expected ratio (o/e) 1.23, 90% interval 1.15 to 1.3. Synonymous variants: 287 observed, 252.43 expected, observed/expected ratio (o/e) 1.14, 90% interval 1.03 to 1.25.
Gene-disease validity (ClinGen):
ClinGen rates the evidence that CCDC78 causes each of these diseases.
centronuclear myopathy (autosomal dominant): Limited.
Homologues: Orthologues: chimpanzee CCDC78 (85% identical), macaque CCDC78 (83% identical), pig CCDC78 (66% identical), dog CCDC78 (61% identical), mouse Ccdc78 (54% identical), rat Ccdc78 (54% identical), guinea pig CCDC78 (52% identical), tropical clawed frog ccdc78 (35% identical), zebrafish ccdc78 (31% identical).
Diseases named in the same sentence as CCDC78 in open-access papers:
CCDC78 is named in the same sentence as 10 diseases in open-access papers, as found by Europe PMC text mining. Sharing a sentence is not in itself a finding about the gene and the disease. The quoted sentences say what the papers report.
centronuclear myopathy (4 papers, 2016 to 2024). Centronuclear myopathy (CNM) is an inherited neuromuscular disorder characterized by clinical features of a congenital myopathy and centrally placed nuclei on muscle biopsy. "Proband B2, besides having two deep intronic variants in the CAPN3 gene, has also a novel mutation in the CCDC78 gene, related to centronuclear myopathy." (PMID 34720847, 2021). "Rare MmD diseases with atypical cores caused by the autosomal-dominant CCDC78 (coiled-coil domain containing 78) mutations are diagnosed also as a centronuclear myopathy." (PMID 33255644, 2020). "CCDC78 mutations and SPEG mutations are implicated in centronuclear myopathy 4 and centronuclear myopathy 5, respectively." (PMID 38988494, 2024).
colon cancer (3 papers, 2022 to 2025). "CCDC78 is identified as a prognosis biomarker in colon cancer through the utilization of a prediction-scoring model." (PMID 40041860, 2025). "CCDC78 gene silencing significantly suppressed the viability, migration, and invasion of colon cancer cells." (PMID 35795065, 2022).
congenital myopathy (3 papers, 2014 to 2024). "In CCDC78-associated congenital myopathy, muscle cores that show aggregates of CCDC78 also contain aggregates of RyR1." (PMID 38732148, 2024).
ciliopathy (1 paper, 2025). A genetic disorder of the cellular cilia or the cilia anchoring structures, the basal bodies, or of ciliary function. "In light of their roles in cilia beating, it is notable that neither CCDC78 nor CCDC33 has previously been associated with motile ciliopathy." (PMID 40027778, 2025). "As such, CCDC78 and especially CCDC33 represent interesting new candidate loci for human motile ciliopathy." (PMID 40027778, 2025).
multiminicore disease (1 paper, 2022). "For example, CNM has been associated with at least seven genes, including MTM1, DNM2, RYR1, TTN, BIN1, CCDC78 and SPEG, whereas RYR1 variations can cause central core disease (CCD), multiminicore disease (MmD), core-rod myopathy, CNM and CFTD." (PMID 35081925, 2022).
myopathy (3 papers, 2021 to 2025). A disease of the muscle in which the muscle fibers do not function properly. "We and others have demonstrated that myopathy-associated variants in CCDC78 lead to the mislocalization of RyR1, a calcium channel protein that localizes to the triad." (PMID 38732148, 2024). "To identify such background differences, we mined WGS of the family members and identified a relatively common variant in CCDC78, a known core myopathy gene, that co-segregates with muscle cores." (PMID 38732148, 2024). "If CCDC78 variants do contribute to myopathy, the effect may relate to the protein’s association with centrioles in MCCs, as CCDC78 was found to localize to centrosomes in HeLa cells." (PMID 40027778, 2025). "A link between CCDC78 and core myopathy has been previously reported, and CCDC78 is included as a core myopathy gene in review publications." (PMID 38732148, 2024). "The relatively common CCDC78 in this family segregates with core myopathy and the more profound skeletal muscle weakness and wasting." (PMID 38732148, 2024). "For probands A1, A2, and B6, we previously found mutations in myopathy-related genes in FKRP, LMNA, and CCDC78, respectively." (PMID 34720847, 2021).
cancer (1 paper, 2019). A tumor composed of atypical neoplastic, often pleomorphic cells that invade other tissues. "For the other four genes (SGCG, CCDC78, OTOP3, and SMPDL3A) in the predicted scoring model, their roles in human cancers have not yet been fully investigated." (PMID 31612869, 2019).
CCDC78 also shares sentences with these, for which no sentence is quoted: Cognitive impairment (1 paper); lung carcinoma (1); tumour (1).